SRSF9 (serine and arginine rich splicing factor 9)
Diseases named in the same sentence as SRSF9 in open-access papers (continued):
Sharing a sentence is not in itself a finding about the gene and the disease.
tumor (19 papers, 2013 to 2024). "Overexpression of SRSF9 was significantly associated with tumor lymph node metastasis and high Dukes stage (P < 0.05)." (PMID 35509101, 2022). "The protein encoded by SRSF9 is part of the spliceosome; a previous study indicates that the proto-oncogene SRSF9 is overexpressed in multiple tumours and that this overexpression can cause the accumulation of β-Catenin54." (PMID 32024818, 2020). "To further understand the molecular mechanism by which SRSF9 exerts its tumor-promoting role in GBM, we employed various strategies and screened out key SRSF9-regulated genes that influence cell cycle." (PMID 38842611, 2024). "Through a correlation analysis of GBM tumor samples, along with cellular assays of SRSF9 knockdown and overexpression, we revealed that SRSF9 positively regulates the expression of CDK1, a cell cycle controller." (PMID 38842611, 2024). "Specifically, the splicing machinery components KHDRBS1, NOVA1, PRPF8, SNW1, SRSF1, SRSF10 and SRSF9 were overexpressed in tumor tissue." (PMID 38049848, 2023). "The tumor grade showed significant correlation with SRSF9 expression in CESC (r = 0.134, p < 0.05), KIRC (r = 0.181, p < 0.001), LGG (r = 0.21, p < 0.001), LIHC (r = 0.14, p < 0.01), OV (r = 0.121, p < 0.05), and UCEC (r = 0.222, p < 0.001)." (PMID 35069733, 2022). "By contrast, the SRSF9 expression was downregulated in tumor tissues of KICH, KIRC, SKCM, and THCA, which was mainly consistent with the analysis before." (PMID 35069733, 2022). "For example, in LUSC, SRSF9 expression had been shown to negatively correlate with the six immune infiltration cells, but positively correlated with purity of tumor." (PMID 35069733, 2022). "In this study, we used public databases, such as The Cancer Genome Atlas (TCGA), Cancer Cell Line Encyclopedia (CCLE), and Genotype-Tissue Expression (GTEx), to analyze SRSF9 expression level among tumor and normal cells." (PMID 35069733, 2022). "In our recent study, we compared the SRSF9 expression in normal and tumor tissues of 33 pan-cancers, using the data from several databases for verification, including TCGA, GTEx, and TIMER." (PMID 35069733, 2022). "In COAD, STAD, and UCEC, SRSF9 expression was positively related to both TMB and MSI, demonstrating that the higher the expression of SRSF9 was, the higher the degree of tumor mutation was and the worse condition the cancer was." (PMID 35069733, 2022). "We found that SRSF9 depletion repressed tumorigenesis and resulted in tumor volumes that were noticeably lower than those in the negative control group, suggesting that SRSF9 exerts its oncogenic role in CRC by regulating cell growth in vivo." (PMID 35509101, 2022). "For further analysis, the data of SRSF9 expression in 33 tumor and normal samples were also obtained from TCGA database and we identified the expression differences of SRSF9 using both the TCGA and GTEx databases." (PMID 35069733, 2022). "This study not only expands our understanding of the roles of SRSF9 in tumor biology but also clarifies the pathogenesis of HCC at the molecular level." (PMID 35971121, 2022). "The results showed that SRSF9 expression was noticeably upregulated in tumor tissues compared with normal tissues (P = 3.491e−13)." (PMID 35509101, 2022). "And only in THCA, SRSF9 had increasing expression in adjacent normal tissues instead of tumor samples, which was contrary to the condition in other cancer types." (PMID 35069733, 2022). "SRSF9, serine/arginine-rich SF, serves as an oncogene involved in diverse biological processes, including tumor cell proliferation, apoptosis, migration, and invasion." (PMID 32984057, 2020). "We further demonstrate that, like SRSF1, SRSF9 is also an oncogene, and is frequently overexpressed in multiple types of human tumours." (PMID 23592547, 2013). "Both SRSF1- and SRSF9-overexpressing cells were tumorigenic and the SRSF9-induced tumours seemed even larger than those of SRSF1." (PMID 23592547, 2013).
tumor (continued). "Interestingly, 16 of the 34 components examined (47.1%) were altered and, in line with our Discovery cohort, KHDRBS1, NOVA1, PRPF8, SNW1, SRSF1, and SRSF9 were also overexpressed in tumor tissue in this external cohort." (PMID 38049848, 2023). "The expression of SRSF9 increased as the tumor grade escalated in KIRC, LGG, LIHC, OV, and UCEC." (PMID 35069733, 2022). "There was a positive correlation between SRSF9 expression and the expression of immune checkpoint-related genes in most tumors, demonstrating that SRSF9 may provide some help for tumor immunotherapy, thereby benefiting on tumor proliferation." (PMID 35069733, 2022). "The higher the expression of SRSF9, the more the purity of tumor cells in various cancers." (PMID 35069733, 2022). "Furthermore, a univariate analysis demonstrated that a variety of factors are unfavorable in HCC, such as SRSF9, Pathologic M, Pathologic T, and tumor stage, while BMI is a favorable factor for HCC." (PMID 35971121, 2022). "However, as the mechanism of SRSF9 varies in various tumors, this conclusion needs to be further studied in each tumor, so as to understand how SRSF9 affects immune functions in a specific tumor and which way SRSF9 accesses to regulate the immune activity." (PMID 35069733, 2022). "However, the mechanism of SRSF9 in a tumor and its relationship with immunity still need further analysis." (PMID 35069733, 2022). "We also demonstrated SRSF9's relationship with the expression of immune infiltration cells, the expression of immune checkpoint genes, TMB, MSI, and other relative immune indicators, inferring that SRSF9 may impact on the tumor development via immune suppression." (PMID 35069733, 2022). "The elevated SRSF9 expression in GBM tumor tissues was also validated at protein level using UALCAN datasets, and a stage-specific increase in SRSF9 expression correlated to advancing GBM stages according to WHO grading." (PMID 38842611, 2024). "The western blotting results suggested that SRSF9 silencing decreased ZEB1, USP22, and N-cadherin expression levels but increased E-cadherin expression levels in tumor tissues." (PMID 39530604, 2024). "To understand the mechanism through which SRSF9 exerts its tumor-promoting effects in CRC, we mined POSTAR2 data, GEO data and TCGA data to screen for potential targets of SRSF9 in CRC." (PMID 35509101, 2022). "Serine/arginine-rich splicing factor 9 (SRSF9) is one of the members of SRSF gene family and related to the tumorigenesis and the progression of tumor." (PMID 35069733, 2022). "One study has shown that tumor growth is promoted by β-catenin protein synthesis, which is enhanced by serine-arginine (SR) rich splicing factor 1 and 9 (SRSF1 and SRSF9)." (PMID 34445242, 2021). "Conversely, application of a similar approach using various methods and antibodies did not reveal consistent differences in the signal abundance and intensity for SRSF1 and SRSF9 in tumor vs. non-tumor tissue." (PMID 38049848, 2023). "But the exact explanation for the connection between SRSF9 expression and tumor proliferation has not been uncovered." (PMID 35069733, 2022). "In addition, tumor xenograft models were constructed by injecting HCT-116 cells with stable knockdown (shSRSF9 sh1, sh2) of SRSF9 into nude mice." (PMID 35509101, 2022). "Our study found that in various cancers, SRSF9 expression had a negative correlation with the content of immune cell and stromal cell in tumor microenvironment." (PMID 35069733, 2022). "Higher SRSF9 expression was significantly positively correlated with malignant characteristics of HCC, such as tumor stage III versus stage I (P = 0.0075); pathologic T3 versus T1 (P = 0.015); histologic grade G3 versus G1 (P = 0.0022), and G3 versus G2 (P = 0.019)." (PMID 35971121, 2022).
tumor (continued). "In addition, Serine and arginine rich splicing factor 9 (SFRS9) can upregulate the expression of GPX4 by binding to GPX4 mRNA, which promote the growth of CRC, while SFRS9 knockdown significantly inhibited tumor growth in nude mice." (PMID 36105219, 2022).
cancer (18 papers, 2013 to 2024). A tumor composed of atypical neoplastic, often pleomorphic cells that invade other tissues. "SRSF9, an RNA-binding protein, is essential for cellular processes and implicated in cancer progression." (PMID 38842611, 2024). "Given that altered chromatin dynamics lead to an accelerated cell cycle, which in turn increases cancer risk, it becomes crucial to further investigate how SRSF9 affects CDK1 and other genes." (PMID 38842611, 2024). "All these evidences suggested that high-expressed SRSF9 was linked with unfavorable clinical outcomes in majority of cancers, especially in LGG, LIHC, KIRP, and UVM." (PMID 35069733, 2022). "While a few players have been identified, the widespread changes in RNA splicing patterns caused by miRNAs’ deregulation of SRSF9 function in various cancers have yet to be identified." (PMID 34769047, 2021). "From these results, we concluded that SRSF1 and SRSF9 are required not only for Wnt-induced but also tumorigenic β-catenin accumulation in cancer cells harbouring mutations that impair β-catenin degradation." (PMID 23592547, 2013). "CD276 expression was associated positively with SRSF9 expression in most cancer types." (PMID 35069733, 2022). "According to the analysis in TISIDB, SRSF9 expression was associated with disease progression in ACC, KICH, KIRC, LUAD, LUSC, and TGCT and SRSF9 was a gene which promotes cancer in KIRC, LGG, LIHC, OV, and UCEC." (PMID 35069733, 2022). "That demonstrated that SRSF9 was a key gene which promotes cancer progression in KIRC, LGG, LIHC, OV, and UCEC." (PMID 35069733, 2022). "In the present study, SRSF9 expression showed significant difference in different molecular and immune subtypes in some cancer types." (PMID 35069733, 2022). "The expression of CD276 was significantly positively correlated with SRSF9 expression in most cancer types." (PMID 35069733, 2022). "To understand the prognostic value of SRSF9 better in pan-cancer, we studied the relationship between SRSF9 expression and various kinds of survival outcomes for each cancer, including OS, DFI, PFI, and DSS." (PMID 35069733, 2022). "Oncogenes are usually highly expressed in cancers, consistent with our results demonstrating that SRSF9 expression is significantly increased in HCC the mRNA level based on TCGA data and at the protein level based on HPA data and laboratory HCC samples." (PMID 35971121, 2022). "To investigate the association between SRSF9 expression and clinicopathological characteristics in various cancers, we assessed SRSF9 expression with the 33 cancers in stages I, II, III, and IV." (PMID 35069733, 2022). "Our study investigated that SRSF9 is a key gene with prognostic value in pan-cancer, deserving more researches' focus." (PMID 35069733, 2022). "The relationship between SRSF9 expression and four DNA methyltransferases was evaluated here, and evidently, SRSF9 expression was closely related to the expression of these genes across human cancers." (PMID 35069733, 2022). "The coefficients indicated that SRSF9 expression showed a positive correlation with low mutation in THYM and THCA (particularly THYM), but high mutation status in other 13 cancer types." (PMID 35069733, 2022). "In the present study, SRSF9 expression had been shown to positively correlate with most of the 47 immune checkpoint genes in most cancers, such as CD276, CD86, CTLA-4, and CD40." (PMID 35069733, 2022). "There are limited data on the relationship between SRSF9 and immune-related factors, so we need more studies on the mechanism of SRSF9 in various cancers to corroborate our results." (PMID 35069733, 2022). "In previous studies, SRSF9 has been reported as a hazard factor for diverse cancers in a lot of studies, and our current findings in pan-cancer were consistence with this recognition." (PMID 35069733, 2022). "First, according to a GSEA, SRSF9 can regulate a variety of cancer-related cellular signaling pathways." (PMID 35971121, 2022).
cancer (continued). "The immune scores in 15 out of 33 cancers showed significant correlation with SRSF9 expression and the stromal scores in 14 out of 33 cancers had significant correlation with SRSF9." (PMID 35069733, 2022). "In general, SRSF9 expression was upregulated in most cancers, such as BLCA, CHOL, and UCEC, which SRSF9 was associated with short survival and severe progression." (PMID 35069733, 2022). "This present study used pan-cancer analysis to explore the role of SRSF9 expression in prognosis and immunity in various cancer types with several public databases." (PMID 35069733, 2022). "SRSF9 promotes the multiplication, invasion, and other malignant biological behavior of many cancers." (PMID 35069733, 2022). "As previous studies indicated, SRSF9 have various effects in different conditions; thus, it is essential to discover the relationship between SRSF9 and pan-cancers from a novel perspective." (PMID 35069733, 2022). "For example, in MESO, the high expression of SRSF9 weakens the body's defense response to cancer cells and the positive regulation of myotube differentiation." (PMID 35069733, 2022). "Continued repression of SRSF9 is dependent on miR-1, which is downregulated in several types of cancers, including bladder cancer." (PMID 34769047, 2021). "Our current studies reveal that the knockdown of SRSF9 in lung fibroblasts inhibits cell proliferation, which is consistent with several studies in cancer cells." (PMID 34445242, 2021). "Increasing evidence demonstrates that SRSF9 regulates progression of different cancers." (PMID 38842611, 2024). "Our careful analysis of this study provides insights into the notable strength of SRSF9 as a prognostic and immunotherapeutic biomarker for pan-cancer in terms of immunology, offering robust and new evidence for potential development of future immunotherapy and diagnostic study." (PMID 35069733, 2022). "What's more, the pan-cancer information about the role of SRSF9 expression in various cancer types is still unknown." (PMID 35069733, 2022). "Specifically, SRSF9 was seem to be a hazard factor in 8 cancer types: ACC (HR = 2.399, p=0.016), HNSC (HR = 1.398, p=0.039), KIRC (HR = 1.639, p=0.031), LGG (HR = 2.018, p < 0.001), LIHC (HR = 1.697, p < 0.001), LUAD (HR = 1.446, p=0.013), SARC (HR = 1.593, p=0.006), and UVM (HR = 3.222, p=0.024)." (PMID 35069733, 2022). "Then, we examined the expression levels of SRSF9 in pan-cancer using the gene data in TIMER." (PMID 35069733, 2022). "Additional studies involving other types of cancer may be undertaken to explore whether the m6A-related manner through which SRSF9 targets DSN1 could be broadly applied as a potential basis for cancer therapy." (PMID 35509101, 2022). "The present study found that SRSF9 had a correlation with TMB in 15 cancers and MSI in 8 cancers." (PMID 35069733, 2022). "Therefore, the results of immunotherapy here further indicate that cancer patients with high SRSF9 expression have better immunotherapy effect." (PMID 35069733, 2022). "At present, few studies have showed the immunological role of SRSF9 in pan-cancer." (PMID 35069733, 2022). "SRSF9 was lowly expressed in C3 type in most of the 11 cancers except ACC, CIAD, and LGG." (PMID 35069733, 2022). "Recently, SRSF9 has been shown to bind an artificial m6A consensus sequence with high affinity, giving us a distinctive perspective from which to explore its role in human cancers, especially CRC." (PMID 35509101, 2022). "SRSF9 has been reported as an oncogenic protein in several cancer cells." (PMID 34445242, 2021). "To verify whether SRSF9 is overexpressed in cancer samples, we performed immunohistochemistry staining on cancer arrays with different tissue origins." (PMID 23592547, 2013). "Thus, SRSF9 plays oncogenic roles in a wide spectrum of cancers." (PMID 38842611, 2024). "Therefore, SRSF9 may be involved in cancer regulation by influencing the regulation of some immune response and function of some cancer cells." (PMID 35069733, 2022).
cancer (continued). "Therefore, SRSF9 can be used as a new drug target for immunotherapy against cancer." (PMID 35069733, 2022). "However, few studies have attempted to determine the biological role of SRSF9 in human cancer." (PMID 35509101, 2022). "SRSF9 expression was negatively related to TMB in THCA and THYM, while it was positively related to TMB in other 13 cancers." (PMID 35069733, 2022). "However, whether SRSF9 has a crucial role across pan-cancer is still unknown." (PMID 35069733, 2022). "In the 33 cancer types, gene set enrichment analysis (GSEA) demonstrated that SRSF9 was correlated with multiple functions and signaling pathways." (PMID 35069733, 2022). "Based on the present study, our conclusion was that SRSF9 expression showed a positive correlation with MMR-related genes, m6A gene, and 4 DNA methyltransferases in most cancers." (PMID 35069733, 2022). "Although chromatin remodeling is known to broadly affect cancer, the specific role of SRSF9 in this process has not been clarified." (PMID 38842611, 2024). "Notably, SRSF9 played an adverse prognostic role in breast (OS, RFS, DSS, and DFS), lung (OS and RFS), ovarian (OS), blood (OS), skin (OS), and esophagus (OS) cancers." (PMID 35069733, 2022). "The 5′-UTR and promoter of SRSF9 (serine and arginine rich splicing factor 9) was significant in DriverPower’s results for pan-cancer and not present in any reference driver sets." (PMID 32024818, 2020). "However, the involvement of SRSF9 as an m6A-binding protein in modulating downstream targets in human cancer has not been investigated previously." (PMID 35509101, 2022). "However, the function of SRSF9 in human cancers, including CRC, has not been studied extensively, and its mechanism of action is even less clear." (PMID 35509101, 2022). "Finally, we showed that the relative proportion of sites with increased vs. decreased editing levels could be partially explained by the differential expression of three RNA binding proteins – RPS14, SRSF9 and DHX15 – in a subset of the cancer types we analyzed (Supplementary Results)." (PMID 26980570, 2016).
SRSF9 also shares sentences with these, for which no sentence is quoted: malignant melanoma (4 papers); squamous cell lung carcinoma (3); bipolar disorder (1); breast tumor (1); colon adenocarcinoma (1); frontotemporal dementia (1); hepatoblastoma (1); infection (1); liver cancer (1); metastatic disease (1); neuroblastoma (1); proximal spinal muscular atrophy (1); renal carcinoma (1); renal clear cell carcinoma (1); schizophrenia (1); squamous cell carcinoma (1).